YPEL1 (yippee like 1)
Description:
May play a role in epithelioid conversion of fibroblasts.
Synonyms: FKSG3
Tractability: No criterion of Open Targets' tractability assessment is met for any kind of drug.
Gene: Protein-coding gene on chromosome 22 (21,697,536 to 21,735,794, reverse strand). Ensembl gene ENSG00000100027.
Subcellular location: Nucleus
Gene Ontology:
Cellular component: nucleus
Genetic constraint (gnomAD): Loss-of-function variants: 7 observed, 17 expected, observed/expected ratio (o/e) 0.41, 90% interval 0.23 to 0.77. The upper end of that interval is the gene's LOEUF score, 0.77, which puts it in group 3 of 6, group 1 being the genes least tolerant of losing a copy. Missense variants: 91 observed, 157.74 expected, observed/expected ratio (o/e) 0.58, 90% interval 0.49 to 0.69. Synonymous variants: 59 observed, 61.01 expected, observed/expected ratio (o/e) 0.97, 90% interval 0.78 to 1.2.
Homologues: Orthologues: chimpanzee YPEL1 (100% identical), tropical clawed frog ypel1 (100% identical), zebrafish ypel1 (100% identical), dog YPEL1 (99% identical), pig YPEL1 (99% identical), mouse Ypel1 (98% identical), macaque YPEL1 (82% identical), Drosophila melanogaster l(2)37Bb (13% identical), Drosophila melanogaster CG3270 (11% identical), Caenorhabditis elegans M04B2.4 (9% identical). Paralogues in human: YPEL2 (97% identical), YPEL3 (88% identical), YPEL4 (79% identical), YPEL5 (38% identical), DMGDH (32% identical), SARDH (30% identical), AMT (24% identical), PDPR (22% identical), L2HGDH (18% identical), FOXRED1 (14% identical).
Diseases named in the same sentence as YPEL1 in open-access papers:
YPEL1 is named in the same sentence as 3 diseases in open-access papers, as found by Europe PMC text mining. Sharing a sentence is not in itself a finding about the gene and the disease. The quoted sentences say what the papers report.
DiGeorge syndrome (1 paper, 2019). "They predicted YPEL1 as a novel gene involved in atypical DiGeorge syndrome (DGS) and validated this prediction in vivo: knock-down of YPEL1 homolog in Zebrafish embryos led to craniofacial defects and confirmed its role in pharyngeal arch morphogenesis." (PMID 31494632, 2019).
cancer (1 paper, 2024). A tumor composed of atypical neoplastic, often pleomorphic cells that invade other tissues. "In various cancer types, YPEL1 may exhibit either oncogenic or anti-tumor functions." (PMID 39668833, 2024).
YPEL1 also shares sentences with these, for which no sentence is quoted: tumor (1 paper).